IL10 (interleukin 10)
Diseases named in the same sentence as IL10 in open-access papers (continued):
Sharing a sentence is not in itself a finding about the gene and the disease.
tumor (continued). "Since IL-6/STAT3/IL-10/TGF-β plays pivotal role in carcinogenesis and EMT39–43,45–48, to verify whether this axis is involved in malignant transformation of tumor cells regulated by transformed macrophage-CMs, we detected the changes of several major indicators in this process." (PMID 33288772, 2020). "WNT5A has dual effects on the tumor microenvironment; it can promote inflammation and chemotaxis of immune cells through activation of the ROR1/Akt/P65 pathway, as well as stimulating the TLR/MyD88/p50 pathway in myelomonocytic cells, to promote synthesis of the anti-inflammatory cytokine, IL-10." (PMID 33034614, 2020). "We have confirmed that indeed moDCs show maturation features when in the presence of supernatant of tumor cells treated with the highly cytotoxic NB-PDT, including upregulation of the maturation markers CD86 and MHC II and increased secretion of IL12-p40, IL-1β, and IL-10." (PMID 32326519, 2020). "The reduced number of tumor-infiltrating CTLs, Th1, and Th17 cells corresponded to the increased plasma levels of TGF-β and IL-10 in B16F10+MSC14d-treated animals, indicating the important role of TGF-β and IL-10 in MSC-mediated suppression of T cell-driven antitumor immune response." (PMID 32695181, 2020). "In our case, this might be explained by the fact that the NB-PDT treated tumor supernatants present TLR4 agonist activity, in agreement with the increase of HSP70 and HMGB1 that are TLR4 agonists themselves and can trigger IL-10 release." (PMID 32326519, 2020). "In females with CC, Th2-type cytokines (IL-10 and IL-13) induce the expression of arginase (ASE), which converts L-arginine into L-ornithine and polyamines, and a reduction in L-arginine is related to the downregulation of the immune response, further promoting tumor progression." (PMID 33425785, 2020). "By nature, PDAC tumours are dense, fibrotic and hypoxic, and combined with the suppression of tumour infiltrating lymphocytes (TILs) by cytokines such as TGFβ and interleukin-10 (IL-10), PDAC is an non-immunogenic tumour." (PMID 32423157, 2020). "For example, Luo and co-workers boosted anti-tumor responses using NPs that co-delivered the TLR3 ligand poly(I:C) and a siRNA specific for the transcription factor STAT (signal transducer and activators of transcription) 3, which induces expression of anti-inflammatory factors like IL-10." (PMID 32917034, 2020). "Therefore, CD4, CD8, Foxp3, GrB, IL10, and CD68 immune cell markers were studied in order to explore if differences around EBV-infected CG cells and EBV+ tumor cells derived from GC cells could be involved in the malignant transformation." (PMID 31963774, 2020). "In our studies, MSCs-IL10 exhibited a strong inhibitory effect on the growth of PANC-1 subcutaneous tumors, and can well inhibited secretion of TNF-α and IL6, the pro-inflammatory cytokines and tumor angiogenesis, so that tumor-bearing mice had longer survival." (PMID 32742480, 2020). "IL-2 may not be the predominant cytokine in a suppressed tumor microenvironment that may be skewed more toward a Th2 or suppressive environment driven by IL-10 and TGFβ." (PMID 32040476, 2020). "The tumour microenvironment (TME) is an inflammatory environment, containing various inflammatory and regulatory mediators such as cytokines (tumour necrosis factor (TNF), Interleukin (IL)-1β, IL-6 and IL-10), as well as chemokines and reactive oxygen species (ROS)." (PMID 32183059, 2020). "THP-1 cells co-cultured with CHS cells secreted high levels of IL-10 and negligible levels of IL-12 with respect to control THP-1, supporting again the notion that CHS cells promote macrophage polarization in the direction of an M2-like pro-tumor functional phenotype." (PMID 32344648, 2020).
tumor (continued). "IL-4 and IL-10 are involved in inducing humoral immunity and they play a role in inducing IgG1 antibodies, which mediate complement-dependent cytotoxicity (CDC) and recruit effector cells for antibody-dependent cellular cytotoxicity (ADCC) as a promising antibody isotype for tumor immunotherapy." (PMID 32764343, 2020). "Next, T cells that have successfully entered the tumor may be functionally repressed by immunosuppressive factors (like PD-L1 and CTLA-4), inhibitory cytokines (e.g., TGFβ, IL-4, and IL-10) and inhibitory cells (e.g., regulatory T cells and tumor-associated macrophages)." (PMID 32983080, 2020). "Although studies exploring TPL2 kinase function in APCs in the tumor environment are lacking, TPL2 activity in macrophage and dendrite cells is associated with increased inflammation, increased IL-10/IL-12 ratio and suppressed CXCL10, MHC II and IFNβ production 80, 82, 92-94." (PMID 32724474, 2020). "MDSCs are the primary producers of IL10 which, in turn, can limit the activity of helper T cells and cytotoxic T lymphocyte (CTL) against tumour cells by different mechanisms including decreasing the expression of major histocompatibility complex (MHC) class I on tumour cells." (PMID 32931721, 2020). "Myeloid Derived Suppressive Cells (MDSC): These are a heterogeneous population of immature myeloid cells, which contribute to tumor progression and potently dampen antitumor immune responses, through mechanisms including the expression of immunosuppressive mediators (e.g., arginase, TGF-β, IL-10)." (PMID 32630708, 2020). "Clearly, one cannot ignore the additional contributions of one or several tumor-induced systemic factor(s) including hormones (secreted from tumor-involved organs), neurotransmitters, galectins, and PGE2 in intra-thymic cytokine (including IL-10)-production by TEC." (PMID 32582141, 2020). "Whether IL-10 has crucial functions in anti-inflammation or in tumor progression similar to that of non-tumor diseases, and whether it is useful in inhibiting tumor development via reducing IL-10 in the TME, deserves future explorations." (PMID 32346605, 2020). "Tumour exosomes have been found to express a number of immunosuppressive molecules including surface-exposed phosphatidyl serine, the death receptor ligands FasL and TRAIL, immune checkpoint inhibitor ligands (e.g., PD-L1), and inhibitory cytokines (e.g., IL-10, TGF-β1)." (PMID 32937961, 2020). "Interestingly, tumor infiltrating NK cells upon engagement with 4-1BBL expressing tumors upregulate surface CD73 expression and acquire immunosuppressive properties via STAT3 resulting in IL-10 and TGF-β production." (PMID 33371456, 2020). "Based on tumor purity, we ascertained that most cytokines are secreted by TAMs and M2 macrophages, and marker sets have significant correlations with CDH11 in STAD, with examples including CCL-2, TGFB1, CXCL12, and MPP2 of TAMs and IL-10, IL1R1, CD163, and MRC1 of M2 phenotype (P < 0.0001)." (PMID 32685527, 2020). "IL-10 depotentiates the immune response against the tumor and excludes APCs from the tumor mass." (PMID 32722054, 2020). "Th2 CD4+ T cells produce IL-4, IL-10, and TGF-β, which may boost tumor progression." (PMID 32595757, 2020). "Furthermore, M-CSF, IL-4, IL10, and TGF-β secreted by tumor cells can trigger the M2 program." (PMID 32487125, 2020). "However, different tumor-related soluble factors (i.e. IL-10, IDO, PGE2, TGF-β1) produced by different tumor-infiltrating immune cells (i.e. M2-macrophages, MDSC, DC, Treg), may negatively affect NK cell activity." (PMID 32423420, 2020). "Neutrophilia provide a favorable tumor microenvironment for cancer progression by secreting many inflammation mediators such as tumor necrosis factor alpha (TNF-α), vascular endothelia growth factor (VEGF), interleukin-2 (IL-2), interleukin-6 (IL-6), and interleukin-10 (IL-10)." (PMID 32911724, 2020).
tumor (continued). "IL-10 may act as a tumor suppressor as it reduces the expression of pro-inflammatory cytokines supporting AML cell proliferation, but it can be also a tumor promoter due to its strong immunosuppressive activity, inhibiting the proliferation of effector T cells while boosting Tregs expansion." (PMID 32443460, 2020). "However, IL-10, differently from IFN-γ, has a controversial role in tumor-immune regulation." (PMID 33077770, 2020). "Furthermore, monocytes and macrophages in IgE-treated rat tumours showed enhanced intracellular TNFα and IL-10 expression, and significantly upregulated TNFα, MCP-1 and IL-10 levels in the bronchoalveolar lavage (BAL) fluid, compared with IgG- or PBS control-treated groups." (PMID 33203088, 2020). "Moreover, although IL-10 (189 ± 78 pg/mL) and CCL1 (3.2 ± 1.9 ng/mL) were detected in the culture media of CD14+ cells from patients with advanced disease, the production of these cytokines was abolished after treatment and tumor regression." (PMID 32824016, 2020). "Moreover, blockade of IL-4 resulted in overexpression of pro-inflammatory cytokines (CXCL10, IL-1β, IL-15, IL-10 and IL-6) and lower expression of immunosuppressive molecules (Foxo3, IDO1 and PD-L1) as compared to cryo-thermal eosinophils + tumour-bearing DCs group." (PMID 31519961, 2019). "Neutrophil IL6 and IL10 expression were not altered by the tumor." (PMID 31712726, 2019). "Hence, our data show that ALCL is a tumor that is dependent on TYK2 for cell survival, that TYK2 is activated through an autocrine loop involving IL-10 and IL-22, and that TYK2 promotes cell survival at least in part through activating the expression of the BCL2 family protein, MCL1." (PMID 30131584, 2019). "The failure of tumor cells to express the IL-10 receptor may explain the failure of IL-10 to promote PD-L1 expression on them (data not shown)." (PMID 31730010, 2019). "IL-10 and TGF-β reduce synthesis of interferon-gamma (IFN-γ) and TNF-α by pro-inflammatory CD4 T cells, thus, lower tumor-specific cytotoxicity of CD8 cells, inhibit the main functions of dendritic cells and NK cells and this way induce tolerance to tumor cells." (PMID 31717542, 2019). "Moreover, DC depletion in vivo lowered tumor-infiltrating CD4+ T-cell expression of CD39, CD49b, CD73, AHR, IL-17, and IL-10 in PDA suggesting that, besides driving select cytokine expression, DC promote this Tr1-like surface phenotype in PDA-associated CD4+ T cells." (PMID 30926808, 2019). "Interestingly, however our data support the combination of both drugs for efficient blockade of IL-10 and thus may add to new data suggesting benefit from combining TAM-receptor blockade and PD-1 blockade in syngenic mouse tumor models." (PMID 31824496, 2019). "Given that the OS is longer in patients with clonally restricted BCR repertoires, future tumor tissue-based translational studies in SKCM should include contextual assessment of BCR repertoire features and prognostically significant B cell subsets (memory, regulatory, IL-10 producing)." (PMID 31138334, 2019). "Interestingly, the level of MCP-1, the cytokine responsible for recruiting fresh macrophages to the tumor lesion, and pro-tumor IL-10 were higher when DLD1shHsp70 cells were used rather than the cells with a normal Hsp70 level." (PMID 31861801, 2019). "CD103−CD11b+ DCTME transfer also failed to accelerate tumor growth in IL-10−/− hosts." (PMID 30926808, 2019). "Finally, there appears to be a unique set of cytokines, including IL-10 and IL-32 g, which are capable of promoting PD-L1 expression on Monos but not on tumor cells, as studied in our previous report and in unpublished data." (PMID 31730010, 2019). "Even more surprising considering their tumor-permissive properties, the CD103−CD11b+ DC subset induces CD4+ T cells to express high TH1- and TH17-family cytokines and transcription factors, including a substantial IFNγ+IL17+ population, which co-expresses IL-10." (PMID 30926808, 2019).
tumor (continued). "In addition, several DAMPs (e.g., HMGB1, S100A4, uric acid) can also enhance the expression of immunosuppressive mediators like interleukin (IL)-10 and indoleamine 2,3-dioxygenase (IDO) in stem cells, thereby inhibiting lymphocyte responses and contributing to tumor promotion." (PMID 31024543, 2019). "However, the EX/MPLA/anti- IL-10 receptor antibody immunisation did not prolong the survival time of TC-1 tumour bearing mice compared with the same vaccine immunisation without IL-10 signalling blockade." (PMID 31277636, 2019). "However, in comparison to HNSCC, different mechanisms explaining this phenomenon were observed, as the most important soluble factors in the tumor microenvironment responsible for the impaired function were designated TNFα and TGFβ, but not IL-10." (PMID 30987228, 2019). "By contrast, PC1/3 KD cells treated with IL-10 did not produce such tumor growth factors." (PMID 31766635, 2019). "Moreover, a high proportion of CD204+/CD163+ macrophages, as well as increasing levels of IL-6, IL-10, VEGF, and MCP-1 secretion by GC-MSC-treated macrophages, synergistically revealed a potent role of GC-MSCs in polarizing macrophages into a pro-tumor (M2) phenotype." (PMID 31801938, 2019). "Indeed, many of the tumor-NK cell escape mechanisms that have been proposed could also be applicable to CSCs, such as heightened secretions of TGF-β and IL-10." (PMID 30646520, 2019). "In contrast, circulating CD8+ T-cells from peripheral blood of HCC patients present high amounts of pSTAT3 which is correlated with high amount of IL-4, IL-6 and IL-10 and low quantity of IFN-γ which may result in abnormal immune surveillance against tumor cells." (PMID 31480382, 2019). "Animal studies of dendritic cell (DC)-derived exosomes showed improved tumor microenvironment by a significant increase in CD8+ T lymphocytes, elevated levels of IFN-γ and interleukin-2, and decrease in CD25+Foxp3+ regulatory T (Treg) cells and of interleukin-10 and TGF-β in tumor sites." (PMID 30108680, 2018). "M1 TAMs exert anti-tumor effects through the release of pro-inflammatory cytokines (IL-1, IL-6, IL-23, TNF-α), whereas M2 TAMs may drive local immune suppression by producing IL-10 and TGF-β." (PMID 29844297, 2018). "It was shown that IL-10 secreted in TME causes changes in classical and nonclassical MHC I molecule expression on the tumor cell surface and thereby inhibits the cytolytic activity of CTLs and NK cells towards tumor cells." (PMID 29954431, 2018). "In addition, the mRNAlevels of IL-4, IL-10, and IL-13 were significantly higher in the tumor tissues whencompared to nontumor muscular tissues (Ps < .05)." (PMID 29950152, 2018). "IL-10 is an immuno-suppressive cytokine and they proved that administration simultaneously with the virus inhibits early immune response to infection resulting in a dampening of anti-viral but not anti-tumor immunity." (PMID 29755464, 2018). "The observation that treatment with SLN-TMZ increases expression of IL-17A without affecting expression of IL-10 suggests that this treatment may also exert positive effects on the anti-tumor immune response by increasing the TH17/Treg cell ratio." (PMID 29364157, 2018). "Our previous work indicated that tumor cell-released autophagosomes (TRAPs), a type of LC3-II+ double-membrane extracellular vesicles (EVs) was sufficient to suppress anti-tumor immune responses by inducing IL-10-producing B cells and immune suppressive neutrophils." (PMID 30563569, 2018). "Additionally, the immune suppressive factor TGFβ, but not IL-10, inhibited CD11b surface expression; TGFβ, IL-4 and tumor cell conditioned medium (TCM) each also suppressed Cd11b mRNA expression." (PMID 30568188, 2018). "In this respect, Pries and colleagues could show that HNSCC tumor cell lines alone could secrete high levels of IL-6/IL-8 but no significant levels of IL-4 and IL-10 in the absence of infiltrating immune cells." (PMID 28443091, 2017).
tumor (continued). "Furthermore, we demonstrated that tumor-derived IL-6 was essential for MDSCs amplification and function in vitro, including promoting T cells apoptosis, inhibiting T cell proliferation, decreasing IFN-γ secretion, and increasing IL-10 production." (PMID 29326716, 2017). "Although all six types of macrophages showed increased phagocytosis of tumor cells in the presence of TTI-621, M(-), M(IL-4) and M(HAGG+IL-1β) macrophages exhibited slightly lower phagocytic capabilities compared to the M(IFN-γ), M(IFN-γ + LPS) and M(IL-10 + TGFβ) subsets." (PMID 29084248, 2017). "The second IL-10 peak observed at day 7 in CD4+ cells prompted us to study IL-10 production by other cell populations at this time point, using tumor-free mice, since equivalent results had been observed in lymphoid organs from tumor-free and tumor-bearing mice." (PMID 27926522, 2017). "Considering that IL-10 could enhance proliferation of MM cells, and reduce Adriamycin-induced cell death, we hypothesized that CuB-mediated inhibition of the STAT3 pathway might synergistically enhance the anti-tumor activity of Adriamycin." (PMID 27418139, 2017). "Due to the important proportion of IL-10+ APC induced by OVA+Imiquimod and considering the role that these cells play in T-cell priming (mainly for DC), phenotypic analyses comparing IL-10+ and IL-10− cells were carried out after vaccination of naive and B16-OVA tumor-bearing mice." (PMID 27926522, 2017). "Thus, we concluded that IFNγ, TNFα, and IL-10 did not alter the expression of B7x in human and murine tumor cell lines." (PMID 29137299, 2017). "Indeed, whereas only 16% of mice with IL-10+ DC rejected their tumor, 67.5% of tumors were rejected in mice lacking IL- 10 in DC." (PMID 27926522, 2017). "Moreover, it has been shown that immunization and simultaneous IL-10 signalling blockade better control tumour growth in a TC-1 mouse model than immunization without IL-10 signalling blockade." (PMID 28810829, 2017). "Moreover, IL-10 which is expressed by TAMs, CD8+ T cells, and tumour cells is an important cytokine in the tumour microenvironment and plays anti-inflammatory, immunosuppressive role that favours tumour escape from immune surveillance." (PMID 29065107, 2017). "However, IL-10 production was not Imiquimod-specific, since clear IL-10 production was detected in poly(I:C)-treated mice and even in some subsets in UT mice (as observed for Tregs), as we previously reported in tumor homogenates." (PMID 27926522, 2017). "It has been reported in a mouse melamona model that tumors engineered to overexpress IL-10 have less macrophage infiltration, lower expression of MHC class I molecules, and a more aggressive tumor phenotype, which could be abrogated by treatment with an anti-IL-10 antibody." (PMID 28716080, 2017). "In the tumor microenvironment, secretion of TGF-β and IL-10 could inhibit the function of T cells." (PMID 27965469, 2017). "When inflammation occurs, tumor cells, macrophages, and other tumor infiltrating immune cells possess high reactive oxygen species (ROS), and secrete chemokines and cytokines such as IL-6, tumor necrosis factor (TNF)-α, IL-1β, IL-10, and transforming growth factor (TGF)-β to tumor microenvironment." (PMID 28629173, 2017). "Thus, increased IL-10 and decreased CCL3 production in ABC DLBCL that display augmented β-catenin activation may add to an immunosuppressive tumor microenvironment." (PMID 26776161, 2016). "Similar to mice in which tumour expression of HMGB1 was silenced or inhibited with recombinant BoxA, mice treated with anti-IL-10 exhibited significantly delayed tumour growth compared to controls, whereas anti-IL-10 did not significantly affect the growth of HMGB1-shRNA-transduced B16 tumours." (PMID 27426915, 2016). "IL-10 might not be critical to the development of early-stage malignant dysplasia but contributes to tumor immune escape after progression to OSCC, while TGF-β1 might be less important for the development of OSCC." (PMID 28053372, 2016).